UCP2 (uncoupling protein 2)
Diseases named in the same sentence as UCP2 in open-access papers (continued):
Sharing a sentence is not in itself a finding about the gene and the disease.
Obesity (continued). "These INDELs and VNTRs could be found in the obesity loci or genes from the earliest GWAS and candidate gene association studies, like FTO, genes in the leptin–proopiomelanocortin pathway, and UCP2/3." (PMID 28615046, 2017). "Green tea EGCG attenuates diet-induced obesity by stimulating UCP2 expression in WAT." (PMID 28659734, 2017). "Studies have shown that blocking the expression of fatty acid-binding protein (FABP4/AP2) could improve inflammation-induced obesity by modulating the upregulated expression of uncoupling protein 2 (UCP2)." (PMID 28770376, 2017). "In heart from rodent and human with obesity, UCP2 and UCP3 may protect cardiomyocytes from death and from a state progressing to heart failure by downregulating programmed cell death." (PMID 27642497, 2016). "Mitochondrial uncoupling protein 2 (UCP2) and 3, members of the larger family of mitochondrial anion carrier proteins have been implicated in several human health conditions including thermogenesis, obesity, diabetes and heart failure." (PMID 26861594, 2016). "Like fasting, obesity is characterized by hepatic lipid accumulation, hyperketonemia, enhanced hepatic glucose production, and decreased hepatic ATP content resulting from increased expression of UCP2." (PMID 27708682, 2016). "The interactions between obesity, uric acid and UCP2 were complicated." (PMID 27273589, 2016). "It seems that AG genotype of UCP2 is an important genetic predisposing factor of metabolic disease including obesity and T2DM; in parallel of these observations, our study is the first study reported the gene-nutrient interactions between −866 A/G of UCP2 gene polymorphism and NAFLD." (PMID 27301474, 2016). "UCP-2 is involved in the regulation of thermogenesis, energy expenditure, and obesity." (PMID 26474757, 2015). "Additionally, increased UCP2 protein was observed in visceral fat of obesity resistant A/J and C57BL/KsJ (KsJ) mouse strains fed a HFD, and studies have described the possible role of UCP2 in energy metabolism." (PMID 26618193, 2015). "It has been proposed that impaired adipose tissue expression of UCP2 may play a role in the pathophysiology of obesity." (PMID 24398006, 2014). "It has been shown that UCP2 have significant effects on obesity in mice, and that its mechanism of action may include alterations of lipid metabolism and metabolic rate." (PMID 25118945, 2014). "A comprehensive bioinformatics analysis found de novo and compound heterozygote sequence variants with a damaging effect on genes previously associated with obesity in mice (LRP2) and humans (UCP2), among other intriguing mutations affecting ciliary function (DNAAF1)." (PMID 25158045, 2014). "Any reduction in the UCP2 mRNA stability could compromise the ability to remove excess calories through thermogenesis, especially in a person with a propensity to obesity from other genetic or environmental influences." (PMID 24804925, 2014). "Unlike UCP1-deficient mice, UCP2 KO mice are resistant to cold exposure and they are not prone to obesity, even when fed a high fat diet, arguing against a role of UCP2 in energy expenditure." (PMID 24945157, 2014). "In a model of obesity-induced diabetes mice (ob/ob mice), UCP2 was markedly upregulated in islets." (PMID 23841103, 2013). "A meta-analysis was performed to determine whether there are any associations between the UCP2 -866G/A, Ala55Val, and UCP3 -55C/T polymorphisms and obesity susceptibility." (PMID 23560041, 2013). "Increasing the expression of UCP-2 may help to prevent the development of hepatic steatosis and steatohepatitis atherosclerosis and obesity." (PMID 24312343, 2013). "Here our results indicate that the UCP2-866G/A polymorphisms are obesity susceptibility loci in populations of European, but not Asian population." (PMID 23560041, 2013). "A protective function for UCP2 has been proposed for a range of diseases, such as ischemia, brain trauma, epilepsy, Parkinson’s disease, diabetes, obesity, and anorexia nervosa." (PMID 22870219, 2012).
Obesity (continued). "Regulation of UCP2 by Sirt1 may also be an important axis that is dysregulated by excess fat to contribute to obesity induced diabetes." (PMID 21549004, 2011). "UCP2 and UCP3 genes cluster on chromosome 11q13 in a region linked to lower resting metabolic rate in humans, which is also syntenic to a region of mouse chromosome 7 linked to hyperinsulinemia and obesity." (PMID 22216339, 2011). "In the present study we evaluated whether the UCP2 and UCP3 genes act as modifiers for obesity and diabetes related risk factors." (PMID 19769793, 2009). "Recent studies have established UCP2 as a key component of beta cell glucose sensing, since it seems to regulate glucose-stimulated insulin secretion, and is also a critical link between obesity, beta cell dysfunction and type 2 diabetes (T2DM)." (PMID 19769793, 2009). "The promoter area variant alleles in UCP2 (rs659366-A) and in UCP3 (rs1800849-T) have been shown to increase gene expression, and thus these alleles might protect against obesity." (PMID 19769793, 2009). "However, the increase in UCP2 expression is notnecessarily related to obesity and insulin resistance, as a highfish-oil diet, which does not result in significant weight gain,is more effective in increasing UCP2 levels than is a highsafflower oil-based diet." (PMID 17389766, 2007). "Energy wastage and protection from obesity were initially suggested to be significant functions of UCP2 and UCP3 due to their homology to UCP1 and their distribution in tissues, such as white adipose tissue and muscle, that could dissipate energy." (PMID 16968550, 2006). "Thus, caution is appropriate in ascribing a whole body thermogenic function and protection against obesity to UCP2 or UCP3." (PMID 16968550, 2006). "Thus, UCP2 might play a central role as an etiological factor in the development of obesity and inflammatory diseases." (PMID 41226458, 2025). "Indeed, the UCP2 overexpression has been described as playing a dual role in obesity." (PMID 41009337, 2025). "Since UCP2 variants might play an important role in energy metabolism, weight regulation, and preventing the accumulation of reactive oxygen species, these conditions were also considered NTD risk factors through obesity and diabetes." (PMID 39081343, 2024). "Moreover, an increased UCP2 expression in white fat in adipocytes may provide a molecular link between type 2 diabetes mellitus and obesity." (PMID 39561140, 2024). "UCP-2, as a protein expressed in the adipose tissue and pancreatic endocrine system, could modulate insulin and glucose metabolism and regulate insulin secretion which could relate it to obesity and diabetes." (PMID 38678284, 2024). "Moreover, UCP2 is well known to be involved in resistance to diet-induced obesity." (PMID 35725366, 2022). "Due to the unique capabilities of UCP2 to promote lipid accumulation in the liver, stimulation of protective neural mechanisms in acute ethanol intake, and reinforcement of insulin resistance, its putative role in the pathophysiology of liver disease and obesity has been accepted." (PMID 33957975, 2021). "Both PPARα and UCP2 could exhibit different expressions according to the level of obesity, and in the state of high lipid accumulation because of HFD, PPARα and UCP2 expression could have increased as an adaptive response to prevent the generation of ROS in the mitochondria." (PMID 34948353, 2021). "Additionally, 11β-HSDH1 knockout mice were demonstrated to be resistant to hyperglycemia caused by obesity and stress, and they were shown to have low resistin and TNF-α levels and high PPARγ and uncoupling protein 2 (UCP2) levels compared with these in the control." (PMID 28386270, 2017). "On the other hand, UCP2 overexpression has been shown to ameliorate both hyperglycemia and obesity-induced endothelial dysfunction, and it may help to prevent the development of atherosclerosis in patients with increased ROS, such as those with diabetes, obesity, or hypertension." (PMID 29163755, 2017).
Obesity (continued). "It has been reported that increased expression of UCP-2 in the vasculature may prevent the development of atherosclerosis in patients with increased production of reactive oxygen species, as in the diabetes, obesity or hypertension." (PMID 25077985, 2014). "Moreover, the promoter region of UCP2 contains Sp1, double E-box, and sterol response elements, which could explain why UCP2 is upregulated in response to high levels of fatty acids, obesity, fasting, leptin, and other conditions." (PMID 25512910, 2014). "Furthermore, UCP-2 might be playing an important role in the regulation of energy expenditure and are likely to contribute to obesity and type 2 diabetes mellitus (T2DM)." (PMID 25077985, 2014). "The meta-analysis revealed that the UCP2-866G/A polymorphism may be a risk factor for obesity in Europeans, but not in Asian subjects." (PMID 24804925, 2014). "Despite these limitations, our results indicate that the UCP2 -866G/A polymorphism may be obesity susceptibility loci in populations of European, but not Asian population." (PMID 23560041, 2013). "However, the impact of UCP2 and UCP3 polymorphisms on obesity is still under debate." (PMID 23560041, 2013). "Our meta-analysis revealed that the UCP2 -866G/A polymorphism may be a risk factor for susceptibility to obesity in subjects of European descent, but not in individuals of Asian descent." (PMID 23560041, 2013). "However, the impact of UCP2 and UCP3 polymorphisms on obesity susceptibility is still under debate." (PMID 23560041, 2013). "Nonetheless, markedly enhanced UCP2 expression in non-transformed cells (primarily induced by fatty acids) may become a significant drawback as shown in pancreatic β cells of obesity-associated (type 2) diabetes." (PMID 21712825, 2011). "Furthermore, if UCP2 does play a role in obesity the higher expression in women might help to regulate lipid oxidation." (PMID 19623254, 2009). "UCP2 is involved in the regulation of energy metabolism and might play a role in obesity." (PMID 19623254, 2009). "However, the data suggesting an effect of UCPs on obesity remains uncertain, with two recent papers reporting no linkage or association with UCP2 or UCP3 alleles, while another reports association of UCP3 alleles with measures of body composition in women." (PMID 16968550, 2006). "A study evaluating the role of UCP-2 and UCP-3 in obesity found that the overexpression of UCP-2 and/or UCP-3 resulted in a decrease in fat mass with an increase in LDL cholesterol in mice, thus highlighting the role of UCPs in alleviating obesity." (PMID 36900198, 2023). "Concurrently, the decomposition of short-chain fatty acids by Lb. induces PPARγ to increase the expression of mitochondrial uncoupling protein 2 and increase the ratio of AMP to ATP, reduce obesity induced by an HFD, and reduce host TG involvement." (PMID 36771383, 2023). "Overall, the reduction of hepatic Ucp2 and Nos2 expression in DIO mice treated with PGG indicated a preventive effect on obesity but also on non-alcoholic steatohepatitis." (PMID 35409415, 2022). "SCFAs were reported to stimulate mitochondrial fatty acid oxidation by activating the UCP2-AMPK-ACC pathway, to prevent and reverse HFD-induced obesity and insulin resistance." (PMID 35807856, 2022). "Further studies are required to clarify the mechanism for the regulation of UCP2 in BAT under HFD conditions, since UCP is a promising therapeutic target for the treatment of obesity and obesity-related diseases." (PMID 32614631, 2020). "For example, m6A negatively mediated UCP2 protein expression and positively mediated PNPLA2 protein expression to regulate obesity development." (PMID 32444598, 2020). "UCP1 homologues, i.e., UCP2 and UCP3, have similar roles and are potential therapeutic target molecules against obesity." (PMID 31312229, 2019).
Obesity (continued). "GHE (3%) supplementation for 9 weeks significantly induced an anti-obesity effect and an increase in the AMPK phosphorylation and PPAR-α and UCP-2 protein expression in obese hamsters." (PMID 31540318, 2019). "In this review we will give a general description of biochemical and molecular characteristics of UCPs and then we will discuss the role of UCP2 and UCP3 in cell death and heart failure in metabolic disease such as obesity." (PMID 27642497, 2016). "The UCP2 gene was mapped to human 11q13 between DS11S916 and DS11S911 markers that significantly related to obesity traits." (PMID 26755944, 2016). "It is reported that PPARα/PGC-1 signaling pathway can be activated by chronic overnutrition and obesity, resulting in the up regulation of fatty acid β-oxidation related genes, such as FATP1, FACS1, UCP2 and UCP335." (PMID 26150313, 2015). "Intriguingly, some of these variants were harboured in genes involved in the pathophysiology of obesity (such as LRP2 and UCP2), providing the foundation for future research in this field." (PMID 25158045, 2014). "Uncoupling protein 1, UCP2 and UCP3 are candidate genes for obesity because they decrease mitochondrial membrane potential and mediate proton leak." (PMID 24804925, 2014). "The target genes regulated by PPARα and involved in lipid metabolism and obesity include CD36, LPL, ACC, ABCA1, CYP4a10, CYP4a14, UCP2, ACO and SCD1." (PMID 24705395, 2014). "For these reasons, UCP2 and UCP3 can be important targets for the treatment of aging, degenerative diseases, diabetes and, perhaps, obesity." (PMID 24796298, 2014). "Moreover, it has been described that UCP-2 overexpression in the vasculature may prevent the development of atherosclerosis in patients with increased ROS, such as in diabetes, obesity or hypertension and ameliorate hyperglycemia-induced endothelial dysfunction." (PMID 25077985, 2014). "Uncoupling protein 1, UCP2 and UCP3 are regarded as candidate genes for obesity and T2DM because they have been found to decrease mitochondrial membrane potential and mediate proton leak." (PMID 23365654, 2013). "Although the physiological roles of UCP2 and UCP3 are less well established, most studies suggested that UCP2 and UCP3 gene clusters could play important roles in energy metabolisms and body mass regulation, and polymorphisms in these two genes might contribute to obesity." (PMID 23560041, 2013). "We propose that the effect of these changes, reflected by the high prevalence of subjects with obesity, high FPG, and serum lipids disorder, was modulated by UCP2 SNPs." (PMID 22533685, 2012). "While mounting evidence has documented the importance of both UCP2 and UCP3 variability in the pathophysiology of different chronic metabolic diseases, such as diabetes and obesity, relatively little is known of their implication in human aging and longevity." (PMID 22216339, 2011). "In addition, Ucp2 gene is in proximity to a cluster of genes related to energy homeostasis and obesity and its promoter region contains several response elements that may explain fatty acid responsiveness and regulation of Ucp2 in response to obesity, fasting and other conditions." (PMID 24281083, 2010). "A review of human genetic studies examining expression of UCP2 or UCP3 and the propensity to obesity suggested that some obesity related phenotypes are significantly associated with these UCPs." (PMID 16968550, 2006). "UCP2 rs660339 and DBC1 rs17060940 also showed a significant role in obesity related-traits." (PMID 38841722, 2024). "In support of this hypothesis, microglia-specific deletion of UCP2, a critical protein in mitochondrial function, prevents HFD-induced obesity and induces cytological markers of increased POMC neuronal activity." (PMID 35742824, 2022). "As the loci of UCP2 and UCP3 genes on mouse chromosome 7 and human chromosome 11 are close, they represent good candidate genes for the quantitative trait locus of diet-induced obesity and diabetes." (PMID 35323702, 2022).
Obesity (continued). "For those reasons, UCP1, UCP2, and UCP3 may be involved in the development of obesity, T2DM, and diabetic complications." (PMID 34712730, 2021). "Due to the role of UCP2 in energy metabolism, the lack of this protein disrupts mitochondrial function in patients with obesity." (PMID 34458651, 2021). "Although it has been originally thought to play a role in no-shivering thermogenesis, obesity, diabetes, and atherosclerosis, it now appears that the main function of UCP2 is to control mitochondria-derived Reactive Oxygen Species (ROS)." (PMID 29367932, 2017). "D11S912 and other STRs flanking UCP2 and UCP3 showed some evidence of linkage with obesity and BMI." (PMID 28615046, 2017). "In summary, we hypothesize that global energy sensors, AMPK, UCP2 and mTORC1, are likely to be influenced by FTO gene regulation, supporting the hypothesis that FTO functions in the process of obesity." (PMID 28859657, 2017). "And our results did not support the association between UCP2 Ala55Val, UCP3 -55C/T polymorphisms and obesity in the populations investigated." (PMID 23560041, 2013). "Nevertheless, phenotypes of mice with inactivated Ucp2 or Ucp 3 genes are not related to defective body weight regulation, indicating that a strategy based only on targeting UCP2 or UCP3 would not be able to counteract obesity." (PMID 24281083, 2010). "Interestingly, the HFD increases UCP2 expression in adipose tissue in obesity-resistant A/J mice, but not in obesity- and diabetes-prone mouse strains." (PMID 35323702, 2022). "However, they were not able to find any association of the UCP2 Ala55Val and UCP3-55C/T polymorphisms with obesity, which is in conflict with our data." (PMID 24804925, 2014). "However, the UCP2 Ala55Val and the UCP3 −55C/T polymorphisms are not candidate loci for susceptibility to obesity in any ethnic population." (PMID 23560041, 2013). "The inability to upregulate UCP2 in response to normal physiological stressors and after feeding raises the possibility that hypothalamic oxidative stress is a key step in obesity pathogenesis, which may be independent of lipotoxicity, at least in this model." (PMID 22916190, 2012). "Associations between UCP2 SNPs and waist or WHR were modest and have not been reported previously, although UCP2 G-866A and A55V have been reported as associated with BMI, and G-866A associated with obesity and adipose tissue levels." (PMID 17397545, 2007). "Double mutant Lepob/ob UCP2-/- mice have improved β-cell function independent of obesity." (PMID 16968550, 2006). "However, UCP2 may protect against atherosclerosis through reduction of oxidative stress and both UCP2 and UCP3 may protect against obesity." (PMID 16968550, 2006). "However, the HFD did not affect UCP2 expression in any tissue in obesity-prone mice." (PMID 35323702, 2022). "Thus, the induction of diabetes and obesity by the HFD seems related mainly to UCP1 and UCP2 expression in adipose tissue, but not to the expression of UCP2 and UCP3 in skeletal muscle." (PMID 35323702, 2022). "Ucp1, Ucp2, and Ucp3 expressed in BAT could generate heat after being activated by fatty acids and could play roles in nonshivering thermogenesis, diabetes, and obesity." (PMID 28665305, 2017).